SMAD4 (SMAD family member 4)
Diseases named in the same sentence as SMAD4 in open-access papers (continued):
Sharing a sentence is not in itself a finding about the gene and the disease.
breast carcinoma (continued). "For exploring whether SMAD4 regulates the aggression and metastasis of breast cancer cells via IBSP, we performed rescue experiments in which cells were co‐transfected with SMAD4 and si‐IBSP." (PMID 39118232, 2024). "In the context of breast cancer, our results revealed that BMPs reduce β-CATENIN protein stability through direct involvement of SMAD4 in MCF7 and T47D cells; in turn, SMAD4 affects the nuclear accumulation and target gene expression of β-CATENIN in MCF7 cells." (PMID 38731813, 2024). "Having found that SMAD4 is required for BMP-induced phosphorylation and degradation of β-CATENIN in MCF7 cells, we wondered whether we could extend our observation to other breast cancer cell lines." (PMID 38731813, 2024). "Similarly to breast cancer, in these tumors, SIRT7 inhibits migration and metastasis formation by deacetylating and inhibiting SMAD4, thus reducing EMT." (PMID 38383727, 2024). "Pathway analysis was performed to determine the pathways through which target genes were involved, and the results revealed that SMAD4, SDMAD7, and VEGFA through the hippo signaling pathway, the TGF-beta signaling pathway, and the cell cycle contribute to breast cancer, respectively." (PMID 36726376, 2023). "In breast cancer, SIRT7 deacetylates and promotes β-TrCP1-mediated SMAD4 degradation." (PMID 37691108, 2023). "Sumoylation of Smad4 at K159 promotes its interaction with the transcriptional corepressor Daxx to repress the transcriptional activity of Smad4, thereby inhibiting the TGF-β-Smad4 signaling pathway and playing the role of a tumor suppressor in breast cancer." (PMID 35216622, 2022). "Monoubiquitination of SMAD4 blocks the interaction of SMAD4 with phospho-SMAD2, and the deubiquitinase USP9X reverses this PTM to activate TGF-β signaling, which in turn promotes migration and metastasis of breast cancer cells." (PMID 35682605, 2022). "Their low expression level upregulates SMAD4 and SMAD2 genes in breast cancer patient samples." (PMID 34297787, 2021). "The link between Smad4 and TGFβ1-dependent autophagy that we observed in NSCLC cells was consistent with studies investigating TGFβ-dependent autophagy in pancreatic ductal adenocarcinoma cell lines and breast cancer cell lines." (PMID 34760883, 2021). "So, the aim of this study was to evaluate whether the methylation pattern of both SMAD4 and PTEN genes was correlated with clinical variables of breast carcinoma." (PMID 33825073, 2021). "However, the TFs such as KLF5 (52%), KLF1 (39%), and SMAD2::SMAD3::SMAD4 (31%) showed significant enrichment (q < 0.1) in gained peaks and FOX family of TFs (FOXA1 28%, FOXA2 28% and FOXF2 17%) in lost peaks in breast carcinomas." (PMID 34090364, 2021). "Also, their diagnostic ability was better than other tumor marker in differentiated early stages and low-grade breast cancer; however, the sensitivity of CEA was more than that of SMAD4 in detection of low-grade tumors." (PMID 33825073, 2021). "Finally, by comparing the expression patterns of components of the TGF signaling pathway and KDM7A in human breast cancer specimens, we discovered that there was statistically significant correlation between KDM7A and TGFB2/SMAD2/SMAD3/SMAD4." (PMID 34249916, 2021). "In breast cancer, SIRT7 could significantly downregulate SMAD4 protein by deacetylating and destabilizing SMAD4 protein without affecting its mRNA level." (PMID 32019578, 2020). "Smad4 is a predictive biomarker of poor prognosis in multiple cancers and the METABRIC data confirm that alterations in the SMAD4 and SNAI2 genes or their altered expression correlate with lower overall survival in breast cancer." (PMID 31481735, 2019). "This hypothesis was verified by in vitro study given that miRNA-transfected MCF-7 breast cancer cells showed decreased expression of the TGF-β-related proteins such as TGFβRII, SMAD4, and SMAD7 compared to control, in concordance with previous literature." (PMID 30989460, 2019).
breast carcinoma (continued). "However, a previous study showed that treatment of OE inhibits the upregulation of SMAD4 and SNAIL2 (Slug), TCF4, VIM (Vimentin), FN (fibronectin) and SERPINE1 genes in a breast cancer cell line and MDCK cells." (PMID 29940929, 2018). "Smad3 and Smad4 form a complex with Snail1, driving EMT in breast carcinomas." (PMID 29228645, 2017). "Supporting a SIRT7-SMAD4 axis in the regulation of breast cancer metastasis, negative correlation between Sirt7 and Smad4 protein levels was repeatedly observed in breast tumors isolated from PyMT; Sirt7tg mice and 4T1 xenograft models." (PMID 28827661, 2017). "In addition, one of the breast cancer cell lines used, MDA-MB-468, has an expression-impairing deletion in the Smad4 gene, hence decoupling Dies1 expression from BMP-signalling." (PMID 27721458, 2016). "In hepatocarcinogenesis, the TGF‐β effector SMAD4 appears to control the transcription of miR‐181b, whereas TGF‐β induces miR‐181a/b at the post‐transcriptional level through SMAD2/3‐dependent miRNA maturation in breast cancer." (PMID 25728313, 2015). "In addition, Smad4 is necessary for the TGF-β-induced EMT and metastasis of breast cancer cells to bone." (PMID 25962958, 2015). "However, BMP2 has been shown to inhibit proliferation in breast cancer cell lines that express SMAD1 and SMAD4." (PMID 22729646, 2012). "Here, we aimed to explore the mutation spectrum of SMAD3 and SMAD4 by screening the highly conserved MH2 domain in the germline DNA in familial and non-familial breast cancer cases as well as age, gender and ethnicity matched healthy population controls." (PMID 21835029, 2011). "Smad4 is essential for TGF-β-mediated inhibition of ERα estrogenic transcription activity, and the inhibition of Smad4 expression switches TGF-β from a repressor to an activator for ERα transactivation in breast cancer cells." (PMID 19943940, 2009). "In Smad4 negative patients of stage III breast cancer, i.e. in patients with positive lymph nodes at primary diagnosis, a trend for an increased 5-year survival was observed." (PMID 16438724, 2006). "For canonical, SMAD4-dependent BMP4 signalling, we generated a signature based on the most upregulated genes minus the most down-regulated genes that were also available in the Metabric dataset and assessed expression and prognostic value in breast cancer patients." (PMID 38689334, 2024). "In the light of this altered response among breast cancer cell lines, our data suggest that SMAD4 may not be sufficient, and the action of some other critical mediators is needed to trigger the phosphorylation and degradation of β-CATENIN." (PMID 38731813, 2024). "In the last step, miRNA microarray analysis was performed to identify differentially expressed miRNAs in each breast cancer subtype, and then it was determined whether they could participate in the regulation of the expression of SMAD3, SMAD4, SMAD5, and SMAD7 selected in previous steps." (PMID 39337574, 2024). "Moreover, many protein post-translational modifications are involved in the progression of breast cancer by regulating the activity of signaling pathways, the activation of most signaling pathways such as NF-κB, TGF-β-Smad4 and PI3K-Akt is a cascade of phosphorylation modification." (PMID 35216622, 2022). "Accordingly, exosomal and non-exosomal miR-1255 may be involved in the malignant phenotype of breast cancer cells or recipient cells via regulating TGF-β receptor-SMAD4 pathways; however, the interaction relationship between miR-1255a and SMAD4 needs further confirmation." (PMID 31763681, 2020).
breast carcinoma (continued). "Moreover, PSG9 enhanced the stability of Smad2, Smad3, and Smad4 proteins by blocking their proteasomal degradation, and regulated the expression of TGF‐β1 target genes involved in EMT and breast cancer progression, thus further amplifying the canonical TGF‐β/Smad signaling in breast cancer cells." (PMID 33377651, 2020). "Limited or no expression of Smad4, TβR-I or TβR-II due to mutation or aberrant expression, which may contribute to lack of TGF-β responsiveness are rarely observed in breast cancers." (PMID 31798766, 2019). "Moreover, the overexpression of FOXM1 in breast cancer can interact with Smad3/Smad4 and inhibit the binding of TIF1γ to Smad4 to prevent its ubiquitination, which can attenuate the inhibitory effects of TIF1γ on TGF-β signaling to promote the metastasis of breast cancer." (PMID 31632911, 2019). "Reduced SIRT1 levels in HMLER breast cancer cells led to increased metastases in nude mice, and SIRT1 reduces the EMT in cancer and fibrosis by deacetylating Smad4 and repressing the effect of transforming growth factor-β signalling on matrix metalloproteinase-7 (MMP-7), a Smad4 target gene." (PMID 27793039, 2016). "We could also conclude that the value of TGFβ1, SMAD4 and TIF1γ expression in breast cancer should not be considered individually but instead combined to serve as an effective prognostic tool for breast cancer." (PMID 26040677, 2015). "HDAC inhibitors may affect the expression/activity of other transcription factors known to regulate ZFP36 transcription such as Smad3, Smad4, AP1, c-myc or NFκB but also some microRNAs, such as miR-29a, which downregulates TTP in a breast cancer model and is known to be upregulated in colon cancer." (PMID 26343742, 2015). "However, germline mutation analysis of SMAD3 and SMAD4, the principle substrates of the TGF-β signaling pathway, has not yet been conducted in breast cancer." (PMID 21835029, 2011). "Given the central role of Smad4 in the signaling of all TGF-β-related superfamily members, reduced or absent Smad4-expression as described here would be expected to alter the signaling not only of TGF-β, but also of the BMPs and activins, which also can inhibit proliferation of breast cancer cells." (PMID 16438724, 2006). "On the other hand, we observed different responses upon BMP stimulation in other human breast cancer cell lines, which suggests that SMAD4 may not be enough, and the critical involvement of other mediators is needed for the responsiveness to this regulation in breast cancer cell lines." (PMID 38731813, 2024). "Indeed, the SMAD4 expression is often lower in breast cancer than in the surrounding nonmalignant epithelium, suggesting that SMAD4 may play a pivotal role in mitochondrial ROS-related cell survival." (PMID 23185428, 2012). "Western blotting of lysates of human breast cancer cell lines revealed that the monoclonal antibody to Smad4 correctly identified a protein of 63kDa, just slightly smaller than ectopically expressed flag-tagged human Smad4 used as a positive control (data not shown)." (PMID 16438724, 2006). "To do this, we followed a complementary approach, where we selected a SMAD4-negative human breast cancer cell line, MDA MB 468, and aimed to determine the effect of BMP stimulation on β-CATENIN protein stability in the absence of endogenous SMAD4 expression." (PMID 38731813, 2024). "Knockdown of Smad4 in VSMC did not affect induction of miR-21; furthermore, miR-21 is strongly induced by TGF-β in the Smad4-null MDA-MB-468 breast cancer cell line." (PMID 19664273, 2009).
colon carcinoma (148 papers, 2007 to 2025). "The most mutated SMAD4 position in human colon cancer is 361, with substitution from an arginine to a histidine (p.R361H)." (PMID 40386410, 2025). "In colon cancer, SMAD4 deficiency results in increased MMP9 expression in colon cancer cells, amplifying the expression of the hypoxia-inducible factor GLUT1, thereby promoting aerobic glycolysis processes." (PMID 38686046, 2024). "Loss of SMAD4 function occurs in the majority of late-stage colon cancers and is associated with aggressive cancer progression." (PMID 38136364, 2023). "SMAD4 has long been associated as a late-stage colon cancer mutation that results in poor prognosis and metastasis." (PMID 38136364, 2023). "The clinical findings were then confirmed by investigating the actions of the activins and FS on cell cycle progression and apoptosis markers in the Smad4-intact SW480 and Smad4-mutated HT29 colon cancer cells." (PMID 34867090, 2021). "This work has major implications for diseases, in particular, pancreatic and colon cancer, where SMAD4 is frequently mutated or deleted." (PMID 34737283, 2021). "Loss of SMAD4 promotes CCL15 expression in colon cancer cells and enables primary tumor invasion and liver metastasis of CRC." (PMID 33799486, 2021). "Our data provide mechanistic insight into the opposite role of Nur77 in colon cancers and unravels the active mode of TGFβ for tumorigenesis in Smad4-deficient colon cancers." (PMID 33990575, 2021). "The authors demonstrated that GSK3 inhibition reactivated TGFβ signaling in SMAD4 mutated cells in colon cancer." (PMID 32429474, 2020). "The Cancer Genome Atlas (TCGA) research network has identified mutations in SMAD4 to be among the most frequently mutated genes in colon cancers." (PMID 30979374, 2019). "SMAD4, mutated mostly in colon cancers, belongs to the SMAD family of genes and acts as a tumor suppressor gene." (PMID 29564063, 2018). "CCL9 seems to be implicated in colon tumor metastasis, as it was increased in the tumor epithelium in a cis-Apc/Smad4 mouse model of spontaneous CRC progression that showed marked invasion." (PMID 29720595, 2018). "In conclusion, we observed association of SMAD4 mutation with patient sex, colonic tumor location, and poor prognosis in CRC cases." (PMID 28267766, 2017). "Reduced expression of SMAD4 is associated with attenuated sensitivity to chemotherapy and poor prognosis of patients with colon cancer in several clinical studies." (PMID 28938919, 2017). "We demonstrated recently that CCR1 plays critical roles in liver metastasis of Smad4-deficient colon cancer in a mouse model." (PMID 25326065, 2014). "High frequency of Smad4 mutation and inactivation is closely associated with increased metastases and poor prognosis in colon cancer." (PMID 23536895, 2013). "A recent study demonstrated that Smad4 loss in colon cancer cells switches TGF-β from a tumor suppressor to a tumor promoter." (PMID 22905131, 2012). "In previous analyses, we were able to show that restoration of Smad4 expression in Smad4-deficient SW480 human colon carcinoma cells was adequate to suppress tumorigenicity and invasive potential, whereas in vitro cell growth was not affected." (PMID 21492476, 2011). "Moreover, inactivation of SMAD4 by loss of the 18q chromosome arm increases expression of VEGF in colon cancer cells." (PMID 38811554, 2024). "The results indicated that Smad4 expression is positively associated with a favorable prognosis of colon cancer and Smad4 may serve as a strong predictor of survival in patients with CRC." (PMID 39664586, 2024). "The loss of the Smad4 promoter accelerates the progression of colon cancer." (PMID 36807774, 2023). "A study reported that SMAD4 mutations or deletions frequently occurred in late-stage colon cancer." (PMID 36142267, 2022). "In addition, some studies have reported that the loss of SMAD4 expression contributed to resistance to 5-fluorouracil in colon cancer." (PMID 36142267, 2022).
colon carcinoma (continued). "This also endows TGFβ with an active pro-tumorigenic action in Smad4-deficient colon cancers." (PMID 33990575, 2021). "However, we did not observe a correlation between TGFβ signal activity and ID1 expression in Smad4-deficient clinical colon cancer samples." (PMID 33990575, 2021). "Indeed, ID1 expression and TGFβ signal activity were positively correlated in Smad4-deficient colon cancer tissues with relatively high Nur77 expression." (PMID 33990575, 2021). "The loss of Smad4 expression is more common in pancreatic, bile duct, appendix, and colon tumors." (PMID 33794845, 2021). "Thus, Smad4-deficient colon cancer cells not only evade TGFβ-induced growth inhibition through Smad4 deletion but also actively respond to TGFβ-induced tumor progression at least through ID1 stabilization, thus reflecting their high malignancy." (PMID 33990575, 2021). "In CRC patients, the SMAD4 mutation rate is 13% in colon cancer and 12% in rectal cancer." (PMID 32580435, 2020). "SMAD4 mutation was associated with colon cancer more so than with rectal cancer (odds ratio 2.85; p<0.001), female sex (odds ratio 1.71; p = 0.02), and shorter overall survival than in wild-type SMAD4 cases (median, 29 months versus 56 months; hazard ratio 2.08; p<0.001 [log-rank test])." (PMID 28267766, 2017). "Similar, albeit more modest effects were observed in SMAD4 mutated SW480 colon cancer cells." (PMID 28717230, 2017). "Furthermore, some studies have shown a strong correlation between the high frequency of SMAD4 gene mutations and colon cancer distant metastasis." (PMID 29065177, 2017). "Similarly in activin treated SMAD4 null SW480 colon cancer cells, NFkB inhibition with wtNBD peptide caused reduced expression of MDM2 paralleled with increased p21 protein expression." (PMID 28418896, 2017). "Additionally, since SMAD4 by itself is frequently mutated and inactivated in colon cancer, it is important to understand the SMAD-independent signaling of activin and TGFβ and the downstream impact on metastatic processes." (PMID 26497569, 2015). "Interestingly, a mouse model deficient for Smad3 has been reported to spontaneously develop colon cancer, and Smad4 deficiency greatly exacerbates a mouse model of colon cancer." (PMID 23555575, 2013). "Furthermore, we hypothesise that Act-AB could be a potential therapeutic target that might supress tumour progression through Smads 1/5/8 in Smad4-mutated colon cancers." (PMID 34867090, 2021). "Transcriptome sequencing analysis of patient colon cancer tissues revealed that Smad4 expression was negatively correlated with Fabp2 and SCD1 expression." (PMID 39664586, 2024). "In colon cancer, miR‐144 inhibits cells proliferation, invasion and migration by downregulating SMAD4." (PMID 36541023, 2023). "We present the first study that differentiates between expression of IRS-1 and 2, RUNX3 and SMAD4 in the tumor epithelial and stromal compartments of colon cancer patients." (PMID 36900240, 2023). "Reduced SMAD4 expression is associated with the activation of the PI3K/Akt pathway and increased VEGF expression in colon cancer cells, which promotes cancer progression and escape from apoptosis." (PMID 37237640, 2023). "Oncogenic mutations activating the WNT signaling pathway were a universal feature of serrated tumors in the model Smad4KO BRAFV600E/+, indicating that the combination of BRAF, SMAD4, and WNT mutations is critical for the progression of serrated colon cancers." (PMID 38136364, 2023). "Deletion of SMAD4 in colonic epithelial cells increases CCL20 expression and chemotaxis of CCR6+ immune cells, contributing to increased susceptibility to colon cancer." (PMID 37685308, 2023).